NLRP9P1 (NLR family pyrin domain containing 9 pseudogene 1)
Synonyms: NOD25; formerly NLRP9P
Gene: Unprocessed pseudogene on chromosome 12 (129,013,336 to 129,016,663, forward strand). Ensembl gene ENSG00000256581.
Diseases named in the same sentence as NLRP9P1 in open-access papers:
NLRP9P1 is named in the same sentence as 1 disease in open-access papers, as found by Europe PMC text mining. Sharing a sentence is not in itself a finding about the gene and the disease.
NLRP9P1 shares sentences with these, for which no sentence is quoted: diabetes (1 paper).